STAT3 (signal transducer and activator of transcription 3)
Diseases named in the same sentence as STAT3 in open-access papers (continued):
Sharing a sentence is not in itself a finding about the gene and the disease.
tumor (continued). "Treatment of PCa cells with CCL5 promotes phenotypic changes, such as epithelial–mesenchymal transition (EMT), along with STAT3 upregulation, phosphorylation, and nuclear translocation, highlighting the CCL5-STAT3 axis as a driver of tumor aggressiveness." (PMID 41228234, 2025). "Knockdown of CPA4 led to decreased phosphorylation of STAT3 and ERK, resulting in suppressed tumor growth and metastasis." (PMID 40805261, 2025). "The IL-6/STAT3 signaling pathway is often constitutively triggered in TNBC, hence promoting tumor development and dismal prognosis." (PMID 40868199, 2025). "The enriched expression of STAT3, VCAM1, and MEF2C at the tumor core and invasive front underscores their role in shaping the tumor–stroma interface." (PMID 41373817, 2025). "GSEAs of the tumor, liver, and skeletal muscle transcriptomics shared an enriched activation of the IL6/JAK/STAT3 pathway in mice with CACS." (PMID 41278737, 2025). "Preclinical studies have identified several sirtuin modulators—both inhibitors and activators—that alter tumor growth, sensitize cells to temozolomide, and regulate pathways such as JAK2/STAT3, NF-κB, and mitochondrial metabolism." (PMID 40710366, 2025). "There is evidence that CAFs recruit both types of MDSCs to tumor sites in lung squamous cell carcinoma (LSCC) by releasing CCL2, which is a crucial activator for the STAT3 signaling pathway." (PMID 40805183, 2025). "Upon binding to LepR, leptin activates the JAK2/STAT3 and PI3K/AKT signaling pathways, inducing tumor cell proliferation, EMT, and enhanced invasive capabilities." (PMID 41164182, 2025). "further identified tumor-derived IL-1α as an upstream mediator of PSC-driven IL-6 release and STAT3 activation in TME." (PMID 40948749, 2025). "M2‐TAM, STAT3/NF‐κB, and TME proteins positively regulate tumor remodeling and angiogenesis through immune system interactions, influencing clinical outcomes." (PMID 41263059, 2025). "In oral squamous cell carcinoma (OSCC), the periodontitis-associated pathogen P. gingivalis activates IL-17+ γδ T cells, which, through STAT3 signaling, induce M2 TAM infiltration, thereby accelerating tumor growth." (PMID 41355895, 2025). "NANOG interacts with a variety of druggable pathways, including HA-CD44, STAT3, PKC, and metabolic pathways, which all contribute to drug resistance and tumor progression." (PMID 40227667, 2025). "We found that tumor-derived LCN2 activated astrocytes through SLC22A17 and JAK2/STAT3 signaling, leading to the secretion of macrophage-recruiting chemokines." (PMID 41436606, 2025). "Therapeutically, this axis can be targeted, as exemplified by a novel STAT3 inhibitor, XYA-2, which co-suppresses MYC and SLC39A10 to elicit anti-tumor effects." (PMID 41583444, 2025). "In vivo, a U2932 tumor-bearing nude mice model was employed to evaluate luteolin’s antitumor efficacy and its effects on JAK2/STAT3 pathway protein expression." (PMID 40051568, 2025). "Mechanistic insights indicate that arsenic sulfide inhibits STAT3 phosphorylation, reduces THBS1 transcription, thereby disrupting the binding between tumor cell THBS1 and T cell CD47, consequently enhancing anti-PD-1 efficacy." (PMID 41019041, 2025). "For example, TAM-derived IL-6, TNF-α and STAT3 signaling were believed to aggravate inflammation of TME and accelerate tumor advancement in PDAC and HCC." (PMID 40380196, 2025). "To further investigate this finding, we conducted silencing experiments on PTPN23, which revealed its functional role in promoting tumor growth, potentially mediated through the IL-6/JAK/STAT3 signaling pathway." (PMID 40570022, 2025).
tumor (continued). "This study explores the combined application of the MDM2 inhibitor (RG7388) and the STAT3 inhibitor (BBI608) to assess their potential to enhance apoptosis and inhibit tumor growth in ALL cells." (PMID 40943567, 2025). "OC is typically classified as a “cold” tumor, often due to IL6-induced immunosuppression through the activation of signaling pathways like STAT3 in cancer cells." (PMID 40427188, 2025). "Autocrine IL-6 maintains MDSC survival through the STAT3-DNMT epigenetic axis, helping them evade necroptosis and accumulate in the tumor microenvironment." (PMID 41010517, 2025). "These actions result in STAT3 and MEK/ERK signaling pathways, which stimulate tumor cell proliferation, invasion, growth and decrease apoptosis." (PMID 41303164, 2025). "Consistent with our in vitro findings, Western blot analysis of tumor tissues revealed that CDN treatment downregulated p-JAK1/2 and p-STAT3 expression while upregulating the pro-apoptotic proteins Bax, cleaved caspase-3, and cleaved caspase-9." (PMID 41585878, 2025). "Collectively, these data highlight the potent anti-tumor effects of the simultaneous inhibition of the Notch1 and JAK1/STAT3 pathways." (PMID 40019515, 2025). "This review highlights the roles of inflammatory pathways, such as NF-κB, STAT3, and PI3K/Akt, in shaping the tumor microenvironment, promoting immune evasion, and facilitating EMT." (PMID 39891849, 2025). "Tumour-derived gamma-aminobutyric acid (GABA), a neurotransmitter, inhibits M1 macrophage polarization via the JAK2/STAT3 pathways, thereby promoting cancer progression." (PMID 40407951, 2025). "This transdifferentiation was propelled by the macrophage migration inhibitory factor (MIF), which was secreted by tumor cells and activated the JAK/STAT3 signaling pathway." (PMID 39891284, 2025). "This translocation then promotes tumor cell survival (NOTCH), regulates metabolism (MAPK), and enhances ATP production (STAT3)." (PMID 39936995, 2025). "At the signal transduction level, these cytokines activate pro-tumorigenic pathways such as NF-κB, STAT3, and MAPK, aligning them with extracellular inflammatory signatures and tumor-promoting transcriptional programs." (PMID 41373662, 2025). "miR-143–3p has been identified as a tumor suppressor in several cancers through regulation of several signaling pathways, including the PI3K/Akt, Wnt/β-catenin, AKT/STAT3 and Ras/Raf/MEK/ERK pathways." (PMID 41080754, 2025). "Leptin promotes cancer cell progression and metastasis by tumor cell proliferation induction and cancer cell apoptosis inhibition via Wnt5a/JNK, STAT3/5 and MAPK/ERK1/2 pathways activation." (PMID 40227577, 2025). "Silibinin is a STAT3 inhibitor which seems to have an adjuvant role in antitumor pathways, although its own molecular mechanism against cancer cells remains not fully explained: it could probably decrease the tumor volume and delay the tumor tissue development." (PMID 41441207, 2025). "Targeting IL-6/JAK/STAT-3 pathway is another therapeutic approach directed against the TME, as IL-6 regulates many tumor-promoting functions." (PMID 40940764, 2025). "IL-6, in the tumor microenvironment of HNSCC, plays a role in mediating EMT and increasing the metastatic potential of tumor cells via the signaling pathway of JAK/STAT3/Snail." (PMID 39941858, 2025). "We further showed that neutrophil-specific STAT3 deletion enhances their anti-tumoral properties, stimulates cytotoxic CD8+ T cell responses that in turn leads to reduced tumor burden." (PMID 40885734, 2025). "The expression of the STAT1-ΔN variant resulted in the disruption of normal spleen architecture by malignant CD3- and CD20-negative tumor cells, which stained positively for both tyrosine-phosphorylated STAT1 and STAT3." (PMID 40287766, 2025).
tumor (continued). "The IL-6/signal transducer and activator of transcription 3 (STAT3) pathway promotes VM formation by upregulating key regulators such as VE-cadherin and MMP2, while also contributing to chemotherapy resistance and tumor recurrence." (PMID 41400702, 2025). "In this respect, it has been indicated that the reduction of IRSp53 expression suppresses cell-related proliferating in cells that v-Src transformed as well as tumor formation in mice, and IRSp53 knockdown suppresses p-AKT/p-Stat3/cyclin D1 signaling pathway." (PMID 41200137, 2025). "Though often overlooked, PD-L1 has several tumor intrinsic functions that have recently been identified to regulate mTOR/AKT, MAPK, STAT3/Caspase 7, integrin β4, MerTK, and BIM/BIK signaling, among others." (PMID 39663510, 2025). "Leptin stimulates tumor proliferation and epithelial–mesenchymal transition via JAK2/STAT3 signaling." (PMID 41164182, 2025). "STAT3 inhibitors, including small molecules like napabucasin and TTI-101, are under investigation for their anti-inflammatory and anti-tumor potential." (PMID 40427086, 2025). "Elevated IL6 has been linked to chemotherapy resistance in ovarian cancer by activating pro-survival signaling pathways, such as JAK/STAT3 and PI3K/AKT, which enable tumor cells to withstand chemotherapy-induced stress." (PMID 40427188, 2025). "IL6 promotes tumor cell proliferation and angiogenesis by regulating the JAK/STAT3 signaling pathway." (PMID 40841364, 2025). "Activated STAT3 and STAT5 transcriptionally induce anti-apoptotic and immunosuppressive genes, facilitating both tumor survival and immune evasion." (PMID 40869364, 2025). "We clarified that UA exhibits obvious anti-tumor capacity in CRC cells by promoting ferroptosis via modulation of system xc- and miR-214-3p/Stat3/GPX4 axis, which eventually depletes glutathione (GSH), inactivates GPX4 and decreases GPX4 expression levels." (PMID 41341590, 2025). "In the tumor microenvironment, the inflammatory factor interleukin‐6 (IL‐6) signals through the IL‐6R/ JAK/ STAT3 pathway." (PMID 39907159, 2025). "In the ECM with higher stiffness, tumor cells such as Huh7 and HepG2 showed significant proliferation, mainly through the activation of ERK, protein kinase B (Akt), and signal transducer and activator of transcription 3 (STAT3) signaling pathways." (PMID 40211368, 2025). "Although functionalization enhances targeting, tumor heterogeneity and the dynamic nature of the TME complicate the consistent and specific delivery of drugs to STAT3‐overexpressing cells." (PMID 40166646, 2025). "Western blot results showed that at the cellular level and in mouse tumor tissues, gefitinib can induce STAT3 phosphorylation, while FMD inhibits gefitinib-induced STAT3 phosphorylation." (PMID 40808689, 2025). "As is well known, triggering tumor cell apoptosis is related to various signaling pathways (PI3K/AKT/mTOR, MAPK, JAK/STAT3, and NF-κB, etc.)." (PMID 41220717, 2025). "Among the mechanisms, one may highlight the JAK2/STAT3 signaling pathway, the activation of the extracellular-signal-regulated kinase (ERK) pathway, the upregulation of acetyl-CoA acetyltransferase 2 (ACAT2), and the induction of IL-8 expression in tumor-associated macrophages (TAMs)." (PMID 40485730, 2025). "In BC, the genes STAT3, CTNNB1, and MYC were upregulated, while TNF was downregulated in tumor tissues." (PMID 41186627, 2025). "Synergistically, these perturbations activate NF-κB/STAT3 signaling, generating a pro-inflammatory cytokine milieu (IL-6, TNF-α, IL-1β) that promotes tumor progression through autocrine-paracrine cascades." (PMID 40919140, 2025). "MiR-hsa-125b-5p affects cell proliferation, migration, and invasion by targeting multiple tumor suppressor genes such as CD147 and TPD52, and it participates in cancer progression by targeting STAT3, BMPR1B, VEGFA, SphK1, CDKN2A, and Sema4D." (PMID 41361055, 2025).
tumor (continued). "The extracts also disrupt tumor-promoting signaling (e.g. AKT, STAT3, NF-κB, MAPK, VEGF/VEGFR) and metastasis-related factors (e.g. MMPs, E-cadherin) and can synergize with chemotherapies (cisplatin, doxorubicin, docetaxel) to enhance cancer cell killing." (PMID 41346617, 2025). "For example, AKT1 participated in seven biological processes, EGFR and STAT3 were involved in six, and SRC contributed to five biological processes, highlighting their essential roles in mediating the anti-tumor effects of steamed PJR." (PMID 41465428, 2025). "STAT3 activation upregulated the oncogenic miRNA miR-216a, which suppressed PTEN, further driving tumor growth and Cisplatin resistance." (PMID 40813689, 2025). "Research has established that activated STAT3, through its interaction with DNA methyltransferase 1 (DNMT1), can enhance the CpG island methylation of several tumor-suppressor genes, thereby contributing to their silencing." (PMID 40083697, 2025). "The levels of signal transducer and activator of transcription 3 (STAT3), phosphorylated‐STAT3 (p‐STAT3), Janus kinase 1 (JAK1), phosphor‐Janus kinase‐1 (p‐JAK1), and PD‐1 in tumor tissues were measured using Western blot (WB)." (PMID 39874200, 2025). "These genetic alterations influence the tumor microenvironment and immune cell infiltration through key signaling pathways such as IL-6/JAK/STAT3, thereby significantly affecting immunotherapy sensitivity." (PMID 40777022, 2025). "Caffeic acid and its derivatives can block pro-angiogenic signaling: caffeic acid phenethyl ester (CAPE) has been reported to suppress STAT3-mediated VEGF expression, inhibiting tumor angiogenesis in renal carcinoma models." (PMID 40808836, 2025). "Spatial transcriptomics revealed SOX18 enrichment at tumor cores and invasive borders, co-localizing with MEF2C, VCAM1, and p-STAT3 in vascular and stromal niches, while SOX30 expression remained low across all tumor regions." (PMID 41373817, 2025). "STAT3 is a key oncogenic and immunosuppressive hub in GBM, and its silencing both slows tumor growth and reverses immune suppression." (PMID 41583439, 2025). "In particular, miRNA-944 will cause increases in proinflammatory cytokines and will upregulate signal transducer and activator of transcription 3 (STAT3), which has a direct contribution to tumor development by enhanced angiogenesis and metastasis." (PMID 40407689, 2025). "Through various molecular pathways, such as MEK–ERK, NF‐κB, and STAT3, macrophages maintain inflammatory responses and immune evasion effects, accelerating HCC progression through interactions with tumor cells." (PMID 40060195, 2025). "In vivo, sh-RNLS reduced tumor volume/weight, as well as RNLS/STAT3, Ki-67, GPX4, and GSH, while increasing MDA." (PMID 40799250, 2025). "To test the therapeutic applicability of STAT3 targeting, we utilized myeloid cell-selective STAT3 antisense oligonucleotide (CpG-STAT3ASO) to target neutrophils in vivo in tumor-bearing mice." (PMID 40885734, 2025). "These antiglioma effects of Kae have been confirmed in vivo using xenograft tumor nude mice models, demonstrating that Kae effectively inhibits tumor growth and enhances the antitumor effects of Gef by targeting the EGFR/SRC/STAT3 signaling pathway." (PMID 41009025, 2025). "Interleukin−6 from Schwann−like stromal cells or M2 macrophages activates STAT3, which partners with phosphorylated TrkB at BDNF enhancers, forming a feed−forward loop that amplifies neurotrophin output and tumour aggressiveness." (PMID 41142827, 2025). "TGFβ has been reported to promote EMT in tumor cells, while TNFα, IL-6, and IL-1 can also promote tumor ETM by upregulating gene expression related to transcription factors such as NF-κB and STAT3." (PMID 39981173, 2025).
tumor (continued). "TAMs promote tumor progression via key signaling pathways, including TGF-β/BMP, TNF-α/Wnt, IL-6/STAT3/IRF4, and Wnt/β-catenin, each regulating cell motility, survival, and immune suppression." (PMID 41459539, 2025). "IL-6 stimulates tumor cell proliferation and survival via JAK/STAT3 signaling and contributes to immunosuppression." (PMID 40746533, 2025). "Brain metastatic tumor cells secrete LCN2, which binds to SLC22A17 on astrocytes, activating JAK2/STAT3 signaling and inducing astrocyte activation and chemokine secretion, thereby facilitating macrophage recruitment." (PMID 41436606, 2025). "Meanwhile, the STAT3 signaling pathway, activated by cytokines such as IL-L6 and growth factors like VEGF, is a central regulator of immune tolerance and tumor-promoting inflammation." (PMID 40843361, 2025). "TNBC cells exhibit hyperactivation of several signaling pathways, including the PI3K/Akt/mTOR, Wnt/β‐catenin, JAK2/STAT3, Ras/Raf/MEK/ERK, Notch, and Hh pathways, all of which contribute to tumor initiation and progression." (PMID 41049266, 2025). "IL-6 is a pleiotropic cytokine that plays a critical role in various physiological and pathological processes, particularly in the tumor microenvironment, where it promotes tumorigenesis and progression by activating the JAK/STAT3 signaling pathway." (PMID 40909292, 2025). "In accordance with cell experiment results, lower protein levels of GPX4, p-Stat3, Stat3, SLC7A11 and SLC3A2 were found in nude mice tumor tissues from UA (40 mg/kg) group." (PMID 41341590, 2025). "The CD3- and CD20-negative splenic tumor cells exhibited immunopositivity for both tyrosine-phosphorylated STAT1 and tyrosine-phosphorylated STAT3." (PMID 40287766, 2025). "DUSP9 negatively regulates PD-L1 expression in multiple tumor cells, and mechanistically, DUSP9 dephosphorylates STAT3 to mediate the inhibitory role." (PMID 41405398, 2025). "Signal transducer and activator of transcription 3 (STAT3) is a key transcription factor that plays a dual role in immune regulation and tumor progression, making it a compelling target for cancer research." (PMID 40636126, 2025). "In order to reduce tumor aggressiveness and enhance outcomes for patients with TNBC, this regulatory axis emphasizes the therapeutic potential of targeting the STAT3/MMP-9 pathway." (PMID 40943427, 2025). "In the tumor microenvironment, STAT3 and ZEB1 form a feedback loop that promotes EMT and enhances the invasive characteristics of tumor cells." (PMID 40016707, 2025). "Research shows that OSM promotes tumor invasion and metastasis by increasing matrix metalloproteinase (MMP) expression and activating the JAK/STAT3 pathway." (PMID 40969371, 2025). "Adipocyte-derived IL6 activates STAT3/NF-κB pathway in TNBC cells to promote the expression and secretion of CXCL1 in TNBC and promote tumor progression." (PMID 40841364, 2025). "Tumor-derived lactate drives transcriptional reprogramming (CCL2, ARG1, IL10, S100A9) in TAMs via the ENSA-K63la/STAT3-pY705 axis, promoting an immunosuppressive environment and immunotherapy resistance." (PMID 39883522, 2025). "Elevated levels of these cytokines are known to promote tumor cell proliferation, angiogenesis, epithelial–mesenchymal transition (EMT), and resistance to apoptosis through activation of NF-κB and STAT3 signaling pathways." (PMID 41470183, 2025). "By binding to IL6ST mRNA, miR‐224‐5p reduces IL6ST expression, suppresses the activation of the JAK2/STAT3 signaling pathway, and ultimately inhibits NSCLC cell proliferation and tumor growth." (PMID 39840666, 2025). "It has been reported that persistently phosphorylated or overexpressed SRC kinase leads to pathological modulation of several tumor cells proliferation-relevant signaling, namely PI3K/AKT pathway, MEK/ERK pathway, and JAK/STAT3 pathway." (PMID 41017855, 2025). "In the tumour microenvironment, the IL-6/JAK/STAT3 axis is stimulated by release of IL-6 from cells such as TAMs." (PMID 39510801, 2025).